HDAC8 (histone deacetylase 8)
Diseases named in the same sentence as HDAC8 in open-access papers (continued):
Sharing a sentence is not in itself a finding about the gene and the disease.
tumor (continued). "Given the significant role of HDACs in tumor progression, metastasis, and drug resistance, we hypothesize that targeting HDAC4 and HDAC8 will enhance doxo sensitivity, promote apoptosis, and inhibit tumor growth." (PMID 40332124, 2025). "Our results demonstrated that HDAC8 was upregulated in tumor tissues compared with normal tissues, that HDAC8 expression was elevated in the high‐protein diet group compared with the normal diet group, and that increased HDAC8 levels were correlated with a poor prognosis." (PMID 40787880, 2025). "Furthermore, our animal experiments revealed that the application of HDAC8 inhibitors effectively reduced the percentage of CD8+ exhausted T cells in tumor sites and improved the efficacy of anti‐PD‐1 therapy." (PMID 40013761, 2025). "Moreover, HDAC1, HDAC7, and HDAC8 are involved in maintaining the stemness of tumor stem cells, promoting TNBC proliferation and migration." (PMID 40091020, 2025). "Additionally, HDAC1, HDAC6, and HDAC8 contribute to tumor invasion by increasing matrix metalloproteinase-9 (MMP-9) expression." (PMID 40091020, 2025). "This suggests that HDAC1 and HDAC8 may have 50 months or even longer impacts on the survival of tumor patients." (PMID 38168914, 2024). "Furthermore, he has studied histone deacetylase 8 (HDAC8), BRCA1, YWHAE-FAME22 rearrangement, Cyclin D1, tumor cell necrosis (TCN), and BCRO as diagnostic markers for uLMS." (PMID 38410101, 2024). "In contrast, HDAC8 inhibition induces relatively low replication stress, but when combined with checkpoint kinase inhibitors, it can elevate replication stress to a lethal level in various tumor types." (PMID 39436709, 2024). "In addition, clustering analysis of the GSE76068 dataset showed that HDAC8 was the most upregulated HDAC in a TKI‐resistant patient‐derived tumor xenograft (PDX) mouse model." (PMID 39073752, 2024). "Moreover, we demonstrated that HDAC8‐in‐PROTACs enhanced the tumor growth‐inhibiting effect of sunitinib in vivo and in vitro." (PMID 39073752, 2024). "Regarding HDAC8 immunostaining, PA cases exhibited nuclear and cytoplasmic staining in 10% of the neoplastic cells demonstrating high immunoreactivity, especially in the periphery of the tumor, while the staining of the internal control (ducts) was strong." (PMID 37887281, 2023). "Since our previous results showed that HDAC8 possesses tumor-supportive properties in BLBC cells, we posited that these effects may result from its ability to positively influence the EMT transcriptional program in chemotherapy surviving cells." (PMID 35016723, 2022). "Because telomerase activity is responsible for senescence escape in tumor cells, these results suggest that HDAC8-mediated stability of hEST1B may contribute to increased tumor cell proliferation." (PMID 36231123, 2022). "RT-qPCR results further depicted reduced expression levels of HDAC8 and SUCNR1 and enhanced IRF1 expression levels in the tumor tissues of mice treated with sh-HDAC8, whereas SUCNR1 expression levels were enhanced, and those of HDAC8 and IRF1 did not change after further oe-SUCNR1 treatment." (PMID 36035205, 2022). "HDAC8 can promote tumor immunity by inhibiting the expression of PD-L1." (PMID 34880761, 2021). "Both of PKM2 and HDAC8 proteins are overexpressed in tumor tissues." (PMID 33279948, 2020). "Consistent with in vitro experiments, in vivo experiments have shown that knocking out HDAC8 can significantly inhibit the growth of tumor cells, while PKM2-K62R mutants instead of PKM2 wild-type can restore tumor cell growth defects caused by HDAC8 deficiency partly (." (PMID 33279948, 2020).
tumor (continued). "According to the findings, among the other markers, HDAC8 oncogene may be used as a potential tumor marker in diagnosis of TNBC tumors." (PMID 32429642, 2020). "Notably, HDAC8 mRNA was also presented with elevated levels in a distinct collection of cell lines, while HDAC8 gene proved to follow an upregulated pattern of activity in tumor versus control specimens." (PMID 30875794, 2019). "Similarly, knockdown of HDAC4 enhanced radiation-induced cell death, that of HDAC6 reduced the migration and invasion activities of all HCC cell lines, and that of HDAC8 repressed tumor cell growth and induced apoptosis." (PMID 30140374, 2018). "High level of AHR expression was noted in tumor cells co-expressing high level of HDAC8." (PMID 27283490, 2017). "HDAC8 has shown to be involved in regulating cell cycle progression of normal and tumor cells." (PMID 28509866, 2017). "Before this, we investigated HDAC8 expression in human tumor samples." (PMID 25695609, 2015). "PKA (protein kinase A) mediated phosphorylation of HDAC8 (histone deacetylase 8), under normal and tumor conditions, recruits EST1B (ever shorter telomeres 1B) and Hsp70/Hsp90 in a complex in a manner which precludes CHIP from ubiquitinating EST1B, which is otherwise a substrate of CHIP." (PMID 24868554, 2014). "Histone deacetylase 1–3 and HDAC8 have been demonstrated to be key for tumour cell proliferation." (PMID 18000499, 2007). "Against NB, small molecule inhibitors with HDAC8 specificity (such as 1-naphthohydroxamic acid, PCI-34051, and 3-benzylamino-benzhydroxamic acid) demonstrated potent effects in vitro and in mice models, causing the induction of cell differentiation and reduction in tumor growth." (PMID 40507292, 2025). "However, downregulation of HDAC8 expression can promote CD8+ T cell infiltration within the tumor." (PMID 40573881, 2025). "Using flow cytometry, RNA-seq, and ChIP-seq analyses, we demonstrate that knocking down or inhibiting HDAC8 impaired murine regulatory T cell (Treg) suppressive function in vitro and in vivo, but promoted conventional host T cell responses, thereby limiting syngeneic tumor growth." (PMID 41379555, 2025). "For example, in KIRC patients with low expression of Purinergic genes, the use of HDAC inhibitors targeting HDAC8, HDAC10, and HDAC11 may help to inhibit the invasive and metastatic ability of tumor cells, which is closely associated with a good prognosis for patients." (PMID 38180750, 2024). "Therefore, inhibiting HDAC8 may be a promising therapeutic approach for protecting kidneys while potentiating the anti‐tumour effects of cisplatin among tumour patients." (PMID 39317961, 2024). "Altogether, the upregulation of Hdac8 in CAF-surviving pG-2 cells, its support of the EMT program as well as its implication in patient relapse-free survival in BLBC patients strongly suggested that elevated HDAC8 levels might confer to the tumor cells chemotherapy-resistant features." (PMID 35016723, 2022). "Therefore, targeting HDAC8 could also be a novel strategy for developing combinatory anti-tumor therapies." (PMID 28509866, 2017). "We next assessed whether the aberrant chromatin status of the Xi also translated into X-linked gene reactivation by assessing XIST together with HDAC8, ATRX, MAGEA6, and TBL1X expression on fresh tumor stamps (including those analyzed above) or tumor-tissue cryosections." (PMID 25653311, 2015). "Together, our data provide evidence that DEC1 and HDAC8 in differentially regulate TAp73 and ΔNp73 expression, suggesting that this regulation may lay a foundation for a therapeutic strategy to enhance the chemosensitivity of tumor cells." (PMID 24404147, 2014).
tumor (continued). "In addition, HDAC8 expression was positively correlated with the genes encoding T‐cell exhaustion‐related genes, including TOX and DDIT3, and negatively correlated with the transcript genes encoding T‐cell activation‐related genes, such as TBX21, in multiple tumor types." (PMID 40013761, 2025). "Subsequent validation of HDAC8 inhibitor and AZD-7762 combination in PDO, mouse xenograft, and PDX models showed high tumor suppression activity with a favorable tolerability profile." (PMID 39436709, 2024). "In our comprehensive analysis of HDACs in DLBCL patients using public databases, we found that the expression levels of HDAC1, HDAC2, HDAC3, HDAC6, HDAC7, HDAC8, and HDAC9 were higher in tumor tissues compared to normal control for the first time." (PMID 38168914, 2024). "Cotreatment with an HDAC8 inhibitor and AZD-7762 suppresses tumor growth in human CRC organoid and mouse xenograft models." (PMID 39436709, 2024). "Collectively, multiple upstream molecules, such as HDGF, AATF, ZHX2, ACSL4, SPIN, HBx, HDAC8, and STAT5, can regulate SREBP-1 expression, activation, and stability to promote HCC proliferation, invasion, and migration for tumor growth and metastasis." (PMID 35912181, 2022). "Using combined analysis of chemical tools and proteomics, another tumor suppressor, AT-rich interactive domain-containing protein 1A (ARID1A), has been introduced as an unbiased candidate substrate of HDAC8." (PMID 36231123, 2022). "HDAC8 inhibition in combination with ICB therapy using anti–PD-L1 antibodies induces effective and durable anti-tumor responses." (PMID 36231123, 2022). "The combination of small molecule HDAC inhibitor Panobinostat and PCI-30451 significantly reduced tumor burden and enhances the sensitivity to BRAF inhibitors proving HDAC8 inhibitors as a promising role in therapeutics." (PMID 33670008, 2021). "HDAC8 was also found to be significantly upregulated in both HCC cell lines and tumor tissues when compared with human normal hepatocytes and corresponding non-tumor tissues." (PMID 34439391, 2021). "When c-MYC and HDAC8 expression is high, as in tumor cells, then the levels of suppressor miRNAs will be lower; conversely, when c-MYC and HDAC8 expression is low, at basal levels, then suppressor miRNA levels will be higher." (PMID 30237861, 2018). "HDAC inhibitors as single agents, via modulation of HDAC1, HDAC3, HDAC8 and HDAC10 function, increased the expression of MHCA and decreased the expression of PD-L1, PD-L2 and ODC on tumor cells." (PMID 29137331, 2017). "CCA tissues had higher expression compared with corresponding matched non-tumor tissues (27.85%, 30.38%, and 32.91% for HDAC2, HDAC3 and HDAC8, respectively; χ2 =10.505, 10.327, 6.609; P<0.05)." (PMID 27705912, 2016). "We selected HDAC2, HDAC3, and HDAC8 to further examine in 79 paraformaldehyde-fixed, paraffin-embedded paired CCA and adjacent non-tumor tissues with immunohistochemistry (IHC)." (PMID 27705912, 2016). "Among HDACs 1-10, class I HDACs (HDAC1, HDAC2, HDAC3, and HDAC8) and HDAC9 were more highly expressed in CCA tissues compared with paired non-tumor tissues (P<0.05)." (PMID 27705912, 2016). "Two HDAC8 inhibitors, PCI34051 and Chrysin, which were identified recently, were reported to inhibit tumor growth." (PMID 23606881, 2013). "Additionally, the fluorescence intensity of PDK4 (green), p-HDAC8 (yellow), and CD20 (deep purple fluorescence) in the mouse tumor tissues was detected using immunofluorescence." (PMID 39004737, 2024).
tumor (continued). "Down-regulation of HDAC-8 increases global acetylation and enhancer acetylation of histone H3 lysine 27 (H3K27), thereby reactivating the production of HCC T cell chemokines and alleviating tumor T cell rejection." (PMID 37304265, 2023). "Although we showed that HDAC2 inhibitors obtained good results in inhibiting tumor growth in cell and animal experiments, HDAC2 is highly homologous to HDAC8, which might result in unexpected side effects due to the paninhibition of HDAC." (PMID 35974388, 2022). "By acting on histones and non-histone substrates, HDAC8 stimulates tumor growth and metastasis by enhancing cell proliferation, suppressing apoptosis, and activating epithelial-mesenchymal transition (EMT)." (PMID 36231123, 2022). "To next test whether the enzymatic activities of these HDACs play a role in tumor cell fitness, we treated pG-2 and HCC1806 cells with specific inhibitors for HDAC8 (PCI-34051) and HDAC4/7 (TMP195) and subsequently assessed tumor cell proliferation." (PMID 35016723, 2022). "Whereas, HDAC8 knockdown inhibited BRAF resistance and decreased tumor size." (PMID 33670008, 2021). "Interestingly, the human orthologue of S. mansoni HDAC8 (smHDAC8), human HDAC8 (hsHDAC8), is less abundant in humans than other class I HDACs (HDAC1 and 3) except in some tumor cells where it is up-regulated." (PMID 33925246, 2021). "Several studies have shown that HDAC8 deacetylates non-histone proteins, thereby affecting the growth of tumor cells." (PMID 33279948, 2020). "Because of this epigenetic dysregulation involving overexpression of HDAC1, HDAC2, HDAC3, and LSD1, we anticipate that the 4SC-202, which specifically targets Class I HDACs (HDAC1, HDAC2, HDAC3, HDAC8) and LSD1, may selectively affect ATRT tumor cells." (PMID 32210076, 2020). "As recent studies showed that HDAC inhibitors act in cooperation with PI3K and mTOR inhibitors to inhibit tumor growth in MYC-driven tumors, we tested the HDAC class I inhibitor entinostat (MS-275) at a concentration ineffective for HDAC8 (500 nM) and combined it with the PI3K or mTOR inhibitor." (PMID 29515255, 2018). "Although HDAC8 inhibitor application significantly slows tumor growth in vivo, the therapeutic effect of treatment with a single HDAC8 inhibitor is not sufficient to induce complete tumor regression, as desired." (PMID 29515255, 2018). "Further investigations are needed to explore whether WMJ-J-09’s anti-tumor mechanisms involves other HDAC isoforms besides HDAC6 and HDAC8." (PMID 29545751, 2018). "In this study, we provide evidences that suggest a plausible mechanism linking AHR and HCC via targeting of HDAC8, which promotes tumor cell growth and may restrain the expression of RB1 tumor suppressors in HCCs." (PMID 27283490, 2017). "BMX (NBM-T-L-BMX-OS01), a histone deacetylase 8 inhibitor (HDAC8i), shows significant anti-cell proliferation effects in CRC cells, human umbilical endothelial cells, lung cancer cells, and glioblastoma cells, and it also exhibits tumor suppression ability in an animal xenograft model." (PMID 36575468, 2022). "In addition, HDAC8 inhibition enforces the immune response mediated by natural killer cells through positive regulation of the transcription of ligands for NKG2D receptor, whose activation is responsible of NK cytotoxicity in tumour cells." (PMID 36077415, 2022). "The expression profiling of 115 chromatin regulators in tumor and adjacent non-tumor tissues from HFD-induced and leptin receptor-deficient (db/db) obese mice identified the overexpression of HDAC8 in tumor tissues, which was confirmed in NAFLD-associated HCC patient samples." (PMID 32443737, 2020). "This HDAC8-dependent mechanism is rather likely to happen in an SMC3 independent manner, as no changes of SMC3 acetylation levels were observed in tumor cells sensitized by HDAC8i treatment." (PMID 35016723, 2022).
tumor (continued). "Previous studies have investigated the regulation by specific HDACs on the PD-L1 expression of tumor cells, including HDAC6 and HDAC8, but the results are not very consistent." (PMID 34365463, 2021). "We then found that the expression of both AHR and HDAC8 was significantly upregulated in both HCC cell lines and tumor tissues compared to human normal hepatocytes and matched non-tumor tissues." (PMID 27283490, 2017).
genetic disorder (10 papers, 2017 to 2024). "CdLS type 5 (CdLS5), a multisystemic genetic disorder, is caused by the HDAC8 (histone deacetylase 8) gene mutations (MIM*300269) on chromosome Xq13.1 with X-linked dominant inheritance." (PMID 38910710, 2024). "The presented link between functional loops and aromatic residues in the vicinity of the active site of HDAC8 provides a conceptual platform by means of which a mechanism for the regulation of HDAC8 can be derived and the mechanism of mutants from genetic disorders such as CdLS can be rationalised." (PMID 34349901, 2021).